FXN (frataxin)
Diseases named in the same sentence as FXN in open-access papers (continued):
Sharing a sentence is not in itself a finding about the gene and the disease.
neuroblastoma (11 papers, 2008 to 2024). Neuroblastoma (NB) is the most common solid, extracranial childhood tumor. "A cellular FA model based on frataxin silencing in human neuroblastoma cells showed that frataxin deficiency affected mitochondrial Ca2+ uptake capacity and reduced ATP production." (PMID 29898895, 2018). "FXN silencing in the neuroblastoma cell model induces slow cell growth associated with cellular senescence and cell cycle arrest at the G1 phase, with increased senescence-associated β-galactosidase (SA-βgal) activity." (PMID 27079523, 2016). "Here, we present the cellular and mitochondrial consequences of frataxin deficiency in a cellular model based on gene silencing in the human neuroblastoma cell line SH-SY5Y." (PMID 24860428, 2014). "By contrast, cell death associated with frataxin deficiency has been reported in a neuroblastoma cell line and rat DRG neurons." (PMID 24860428, 2014). "Actually, another PPAR-γ agonist, azeaolyl PAF, has the ability to increase the expression of frataxin in human neuroblastoma cells, and in primary fibroblasts from FA patients and from healthy controls." (PMID 29898895, 2018). "To investigate the consequences of frataxin depletion in cells and mitochondria, we generated FXN-silenced clones of the human neuroblastoma SH-SY5Y cell line using five different shRNA targeted to five different sites on the FXN gene." (PMID 24860428, 2014). "In this context, we studied the in vitro effect of deferiprone in control and FRDA patient cultured skin fibroblasts and in a shRNA frataxin-depleted neuroblastoma-derived cell line (SK-N-AS cells)." (PMID 18558000, 2008). "Based on this approach, researchers have developed different disease models using either RNA interference in human neuroblastoma cells or Caenorhabditis elegans, or expressing a reduced amount of human FXN in the humanized mouse model YG8R." (PMID 27079523, 2016). "Here, we investigated the mitochondrial and cell consequences of frataxin depletion in a cellular model based on frataxin silencing in SH-SY5Y human neuroblastoma cells, a cell line that has been used widely as in vitro models for studies on neurological diseases." (PMID 24860428, 2014). "Dysregulation in these contacts have been previously reported in FRDA in a neuroblastoma cell line and in a drosophila model where the FRDA phenotype was mimicked with FXN hairpins." (PMID 38420191, 2024). "In order to investigate the effects of a lack of frataxin on cellular homeostasis, we developed a cell model of frataxin deficiency by FXN gene silencing in the human neuroblastoma cell line SH-SY5Y." (PMID 24860428, 2014). "Interestingly, in SKNBE neuroblastoma cells, Pioglitazone incubation for 96 hours at 10 μM increased PGC-1α and SOD2 levels as well as frataxin amount." (PMID 20383327, 2010). "Therefore, we studied neuroblastoma-derived cell lines (SKNAS), using shRNA to silence frataxin." (PMID 19158945, 2009).
cardiac hypertrophy (9 papers, 2015 to 2024). "Mice with conditional loss of FXN in the heart develop cardiac hypertrophy as early as 5 weeks of age, followed by transition to dilated cardiomyopathy and heart failure by approximately 8 weeks of age." (PMID 28542596, 2017). "FXN deficiency-induced iron overload is strongly associated with myocardial hypertrophy." (PMID 35264205, 2022). "We studied mice with systemic knockdown of frataxin (shFxn), which display motor deficits and early mortality with cardiac hypertrophy." (PMID 39171530, 2024). "Intraperitoneal injection of 1.7 μg LGF for three weeks improved motor coordination assessed by rotarod test, demonstrated neuroprotection in lumbar region and reversed cardiac hypertrophy in a YG8R mouse model mediated by increased protein level of frataxin." (PMID 35745683, 2022). "Lastly, our PAESe in a similar manner to FXN-OE cardiomyocytes demonstrated reduced cardiac hypertrophy in response to DOX treatment." (PMID 33912028, 2020). "Cardiac hypertrophy is manifest by day 45 in FXN KO animals." (PMID 28542596, 2017). "The "signaling pathways" for cardiac hypertrophy and the many involved biomolecules have attracted attention for several years, but the cited studies did not consider frataxin deficiency and how it might cause heart disease in FA." (PMID 25738292, 2015).
heart failure (7 papers, 2017 to 2024). Inability of the heart to pump blood at an adequate rate to meet tissue metabolic requirements. "Brain natriuretic peptide (BNP) levels, which can indicate heart failure, were unchanged by frataxin depletion or NAD+ precursors." (PMID 39171530, 2024). "Cardiomyopathy and subsequent cardiac failure is the most common cause of death in FRDA patients, where expanded GAA repeats in intron 1 of the frataxin gene (FXN) cause its partial deficit." (PMID 31049138, 2019). "Acetylation was temporally progressive and paralleled evolution of heart failure in the FXN KO model." (PMID 28542596, 2017). "NMN treatment normalizes both CE and VC in the FXN-KO heart failure model." (PMID 32411700, 2020). "Administration of nicotinamide adenine dinucleotide–positive (NAD+) precursors has shown promise in human mitochondrial myopathy and rodent models of heart failure, including mice lacking frataxin in cardiomyocytes." (PMID 39171530, 2024). "We used an established conditional mouse model of FRDA heart failure with absence of FXN in the heart (FXN KO) compared to healthy littermates (FXNfl/fl)." (PMID 28542596, 2017). "We initially hypothesized that frataxin depletion and the subsequent deleterious effects on mitochondria might lower the mitochondrial NAD+ level and that impaired mitochondrial function would be a key driver of heart failure." (PMID 39171530, 2024). "In FXN-KO hearts, a large proportion of PVA is consumed as PE, rather than ME, which indicates greater energy wastage in heart failure." (PMID 32411700, 2020).
hypertrophic cardiomyopathy (7 papers, 2016 to 2024). A condition in which the myocardium is hypertrophied without an obvious cause. "Clinical findings support the notion that human patients with FRDA display reduced FXN levels, develop life-threatening hypertrophic cardiomyopathy." (PMID 33912028, 2020).
Huntington disease (6 papers, 2013 to 2025). Huntington disease (HD) is a rare neurodegenerative disorder of the central nervous system characterized by unwanted choreatic movements, behavioral and psychiatric disturbances and dementia. "Unlike other trinucleotide repeat disorders, such as Huntington disease, the large expansions of GAA·TTC repeats in FRDA do not produce a change in the frataxin amino acid sequence, but they produce reduced levels of normal frataxin." (PMID 23533785, 2013).
anemia (4 papers, 2010 to 2023). A reduction in the number of red blood cells, the amount of hemoglobin, and/or the volume of packed red blood cells. "Although vorinostat did not seem to cause anemia or decreased level of hemoglobin in the mice it may affect iron metabolism through other means such as increased expression of ferritin H and frataxin." (PMID 27196668, 2016). "The lack of efficacy we observed with anemia was surprising but in line with our previous cell culture results, where we found that hypoxia is only beneficial to FXN null cells when iron uptake pathways are activated." (PMID 37260376, 2023). "The function of FXN is not yet very clear in our eyes since the patients of FRDA have no systemic anemia, indicating that 2Fe–2S containing FECH is mildly, if some, affected." (PMID 37288145, 2021).
iron deficiency (4 papers, 2010 to 2024). "Iron depletion with iron chelator DFO decreases TFAP2 mRNA and FXN mRNA levels in vitro in cell lines, suggesting that frataxin-deficiency-caused cellular iron deficiency may impact TFAP2 mRNA, leading to a further decrease in FXN mRNA." (PMID 38920668, 2024). "Interestingly, the sensor node k/o model agrees with experimental data that in frataxin k/o mice heme is decreased, TfR1 is upregulated and iron uptake via Mfrn is increased, leading to cytosolic iron-deficiency and mitochondrial iron overload." (PMID 28166223, 2017).
iron overload (4 papers, 2011 to 2025). "Iron overload is commonly reported in FRDA pathology due to the pivotal role of the FXN protein in modulating iron concentrations and in facilitating the biosynthesis of iron-sulfur (Fe-S) clusters within mitochondria." (PMID 41318543, 2025).
neuropathy (4 papers, 2014 to 2026). A disorder affecting the nervous system that manifests with pain, tingling, numbness, and/or muscle weakness. "Frataxin deficiency causes severe changes in sensory peripheral nerves, and it is uncertain that FA neuropathy is solely the result of the lesion in DRG." (PMID 27142428, 2016). "This neuropathy is caused by mutations in the FXN gene that encodes frataxin." (PMID 24860428, 2014). "Indeed, we identified four families with neuropathy as the predominant or sole clinical feature, harboring variants in genes causing complex neurological syndromes, such as SPG7, FXN, and ATM." (PMID 39776111, 2025).
ovarian carcinoma (4 papers, 2007 to 2026). A malignant neoplasm originating from the surface ovarian epithelium. "In one report, over-expression of frataxin was associated with resistance to cis-platinum in ovarian carcinoma cell lines." (PMID 19455237, 2007). "Similarly, in ovarian cancer stem-like cells (OCSLCs), elevated levels of frataxin (FXN) correlate with increased ferroptosis susceptibility." (PMID 41601687, 2026). "The expression of ALAS2 and HMBS involved in iron utilization was associated with improved PFS in ovarian cancer, whereas expression of ABCB7, ALAD, FXN, UROS, ISCU, and CPOX in this process was associated with poor PFS in ovarian cancer." (PMID 38186569, 2023). "It was previously shown to increase FXN gene expression in a cisplatin-resistant ovarian carcinoma cell line." (PMID 23418481, 2013). "The expression of ALAS2, HMBS, and FXN involved in iron utilization was associated with improved OS in ovarian cancer, whereas the expression of ALAD, ALAS1, and CPOX in this process was associated with poor OS in ovarian cancer." (PMID 38186569, 2023).
sensory ataxia (4 papers, 2015 to 2023). Any ataxia in which the causes of the disease is a perturbation of the sensory system, leading to its dysfunction. "Friedrich's ataxia (FRDA) is a single-gene inherited recessive neurodegenerative disease caused by expansion of triplet nucleotide GAA repeats in the first intron of the frataxin (FXN) gene, characterized by progressive cerebellar and sensory ataxia." (PMID 35264205, 2022).
colon carcinoma (3 papers, 2024 to 2025). "Thus, frataxin’s expression in colon cancer cells was visualized after exposure to electroporation-supported drug delivery." (PMID 38794222, 2024). "There are studies indicating that frataxin may act as a tumor-suppressor protein, as demonstrated by using frataxin overexpression in colon cancer models (exhibiting growth inhibition) or mice with disrupted hepatocyte frataxin expression (that develop liver tumors)." (PMID 40724837, 2025).
glioma (3 papers, 2019 to 2024). A benign or malignant brain and spinal cord tumor that arises from glial cells (astrocytes, oligodendrocytes, ependymal cells). "Interestingly, previous research also showed that Frataxin could promote glioma growth." (PMID 38506080, 2024). "We then tested these FXN-activating ASOs in more cell lines from various tissue origins including HEK-293T (kidney), JHH2 (hepatocellular carcinoma) and U87 (glioma) and observed significant FXN mRNA increase by S10+2, S10_L6 and S30." (PMID 36511872, 2022). "Then, we knocked down ELTD1 with short hairpin RNAs in U-87MG and U-138MG glioma cells and found that the protein levels of p-JAK, p-STAT3, HIF-1α, and Frataxin notably decreased compared with the levels in the control group." (PMID 31554859, 2019).
Glucose intolerance (3 papers, 2020 to 2025). Glucose intolerance (GI) can be defined as dysglycemia that comprises both prediabetes and diabetes. "As expected, YG8R mice showed more severe glucose intolerance than Y47 mice after fasting, indicating that FXN deficiency aggravated lipid-metabolic disorders caused by excessive nutrition." (PMID 39191875, 2024).
Hyperglycemia (3 papers, 2014 to 2024). An increased concentration of glucose in the blood. "The underlying mechanism of FXN deficient-induced hyperglycemia in FRDA is, however, poorly understood." (PMID 39191875, 2024). "Frataxin is involved in iron metabolism, thus, depletion of frataxin leads to increased levels of ROS within pancreatic islets, which could lead to both hyperglycemia and impaired insulin secretion." (PMID 25198290, 2014).
hyperlipidemia (3 papers, 2020 to 2022). "Hyperlipidemia, impaired energy expenditure, insulin sensitivity, as well as higher plasma leptin are all shown in the FXN knock-in/knock-out (KIKO) mouse, which mimics T2D-like symptoms." (PMID 35677823, 2022). "Here we report that the FXN knock-in/knock-out (KIKO) mouse shows hyperlipidemia, reduced energy expenditure and insulin sensitivity, and elevated plasma leptin, recapitulating T2D-like signatures." (PMID 31974344, 2020).
Mitochondrial myopathy (3 papers, 2013 to 2024). "ATF4 has been considered an important transcription factor in mitochondrial myopathy in mice and humans and in the mouse heart depleted of FXN." (PMID 35531957, 2022). "Along with reduced frataxin expression in skeletal muscle tissue our spectroscopy data suggest primary involvement of skeletal muscle in FRDA patients even without pathological hallmarks of mitochondrial myopathy." (PMID 23922695, 2013).
Obesity (3 papers, 2020 to 2024). Accumulation of substantial excess body fat. "Deletion of FXN in mice leads to an impaired oxidative metabolism accompanied by a higher predisposition of these animals to suffer from high-caloric diet-induced obesity, but again, to date, this has not been explored in human obesity." (PMID 32752277, 2020). "ALPK3, HLF, FXN, and SPTAN1 are the only genes that have never been linked to obesity." (PMID 35677823, 2022).
optic atrophy (3 papers, 2015 to 2025). A disorder characterized by loss of optic nerve fibers. "Even though optic atrophy does occur in FRDA patients it is uncommon, and a primary OPA1 diagnosis is further supported by frataxin level only in the carrier range." (PMID 26338206, 2015).
Sensory neuropathy (3 papers, 2020 to 2021). Peripheral neuropathy affecting the sensory nerves. "Therefore, actin rod formation could contribute to the axonal sensory neuropathy observed in frataxin-deficient DRG neurons from the YG8R mouse by blocking axonal transport." (PMID 32251310, 2020). "Subsequently, the same laboratory used a parvalbumin conditional K.O. of FXN to show that FXN delivery through an AAV vector leads to a recovery of sensory neuropathy in this model." (PMID 33670433, 2021). "Expression of human FXN upon intravenous injection of an AAV-FXN vector in the mouse model extended lifespan, improved cardiac function and prevented peripheral sensory neuropathy." (PMID 34114603, 2021).
Cerebellar atrophy (2 papers, 2023 to 2025). Cerebellar atrophy is defined as a cerebellum with initially normal structures, in a posterior fossa with normal size, which displays enlarged fissures (interfolial spaces) in comparison to the foliae secondary to loss of tissue. "Progressive cerebellar atrophy was associated with progressive ataxia only in four cases (40%; ATM, CACNA1A, FXN, and SAMD9L)." (PMID 40326640, 2025).
hereditary spastic paraplegia (2 papers, 2021 to 2022). Hereditary spastic paraplegias (HSP) comprise a genetically and clinically heterogeneous group of neurodegenerative disorders characterized by progressive spasticity and hyperreflexia of the lower limbs. "A further 43 probands were fully or partially explained by structural variants or simple tandem repeat expansions in the genes HTT or FXN in probands with hereditary spastic paraplegia." (PMID 34758253, 2021).
ischemia (2 papers, 2018 to 2023). A hypoperfusion of the BLOOD through an organ or tissue caused by a PATHOLOGIC CONSTRICTION or obstruction of its BLOOD VESSELS, or an absence of BLOOD CIRCULATION. "Taken together, our results show that FXN overexpression in Müller cells improves RGC survival after acute ischemia/reperfusion injury and this is associated with an increased expression of antioxidant enzymes and neurotrophic factors." (PMID 29555919, 2018). "As FXN expression is increased during ischemic injury, and loss of astrocyte‐specific FXN expression leads to aberrant oxidative stress, therapies that maintain or increase FXN expression may be neuroprotective in patients experiencing ischemia." (PMID 36550598, 2023). "Herein, we have summarized the importance of astrocytic mitochondrial function and the astrocytic mitochondria protein FXN in ischemia‐induced changes in metabolism, mitochondrial dynamics, and cerebral blood flow." (PMID 36550598, 2023). "We also examine how the astrocytic mitochondrial protein FXN is a possible pharmacologic target for regulating the response to ischemia." (PMID 36550598, 2023). "Elevated oxidative stress increases expression of the mitochondrial enzyme frataxin in the retina, and its overexpression is neuroprotective after ischemia." (PMID 29555919, 2018). "Given the role of FXN in mitochondrial function, FXN in astrocytic end‐feet may contribute to astrocytic Ca2+ signaling and cerebral blood flow regulation during ischemia." (PMID 36550598, 2023). "In addition, special focus will be given to the role of the mitochondrial protein frataxin in activated astrocytes during ischemia and its putative role in the pharmacological management of cerebral ischemia." (PMID 36550598, 2023). "Specifically targeting astrocytic FXN may protect astrocytic mitochondria from damage and dysfunction to preserve and support the neuroprotective role of astrocytes in ischemia and prevent ischemic damage." (PMID 36550598, 2023). "However, the mechanism by which FXN levels are regulated in astrocytes under physiological and pathological conditions and during ischemia is not fully understood." (PMID 36550598, 2023). "Gene expression ratios of the antioxidant enzymes Gpx1, Sod1 and Sod2, Cat and Hmox1 were evaluated 24 hours after ischemia by means of qRT-PCR to determine whether increased antioxidative capacity might be involved in FXN-mediated neuroprotection." (PMID 29555919, 2018). "We next examined whether the expression of FXN in Müller cells increased survival of RGCs after acute ischemia/reperfusion." (PMID 29555919, 2018). "Expression of the cytokines Tnf-α and Il-1β and of the gliosis marker Glast, Vim, Gs and Gfap were evaluated 24 hours after ischemia by means of qRT-PCR to determine whether inflammation or an altered gliotic response is involved in FXN-mediated neuroprotection." (PMID 29555919, 2018).
psoriasis (2 papers, 2019 to 2023). An autoimmune condition characterized by red, well-delineated plaques with silvery scales that are usually on the extensor surfaces and scalp. "Here we show that DMF, approved for use in humans for multiple sclerosis and psoriasis, dose-dependently induces both FXN expression whose deficiency is the only cause of FA, and also induces mitochondrial biogenesis." (PMID 31158268, 2019). "The study will contribute to the understanding of the ability in-vivo of DMF, at currently approved doses for MS and psoriasis, to increase the expression of the FXN gene and to increase frataxin protein." (PMID 37746147, 2023).
Cerebral atrophy (1 paper, 2025). Atrophy (wasting, decrease in size of cells or tissue) affecting the cerebrum. "Duplications of ZNF451 and FXN (Case 23) suggest altered transcriptional regulation and DNA repair mechanisms underlying cerebral atrophy and dental anomalies." (PMID 40869915, 2025).